TNC (tenascin C)
Diseases named in the same sentence as TNC in open-access papers (continued):
Sharing a sentence is not in itself a finding about the gene and the disease.
leiomyoma (2 papers, 2007 to 2019). A well-circumscribed benign smooth muscle neoplasm characterized by the presence of spindle cells with cigar-shaped nuclei, interlacing fascicles, and a whorled pattern. "They identified several proteins up regulated in the leiomyoma: POSTN, TNC, COL3A1, COL24A1, and ASPN." (PMID 31100862, 2019).
lymphoma (2 papers, 2018 to 2025). A malignant (clonal) proliferation of B- lymphocytes or T- lymphocytes which involves the lymph nodes, bone marrow and/or extranodal sites. "Indeed, we found a particularly strong and diffuse expression of tenascin-C in AITL, which is well recognized to show the most prominent vascular component among lymphomas." (PMID 29515769, 2018).
Medullary Thyroid Carcinoma (2 papers, 2016 to 2021). "Reexpression of TNC has also been observed in papillary and medullary thyroid carcinomas." (PMID 33564303, 2021). "Tenascin C, EGFR, E-cadherin, TTF-1-expression, and their correlations with RET mutation status were investigated in 30 patients with medullary thyroid carcinoma (MTC) (n = 26) or C-cell hyperplasia (n = 4)." (PMID 27409604, 2016).
meningioma (2 papers, 2024 to 2025). A generally slow growing tumor attached to the dura mater. "Statistically significant differences were also observedfor TNC+ EVs (FC = 27.2, p < 0.01)and the subpopulation TNC+/CD9+ (FC = 34.5, p < 0.01) when compared to meningioma patients." (PMID 40056466, 2025). "However, the expression of tenascin-C (TN-C), an extracellular matrix glycoprotein, in canine meningiomas has not been performed." (PMID 39453053, 2024).
metastasis (2 papers, 2015 to 2018). The spread or migration of cancer cells from one part of the body (where they first appeared) to another. "Consequently, tenascin C protein expression in primary CRCs revealed that a high staining intensity was correlated with synchronous liver metastasis and its staining intensity was an independent prognostic factor to predict postoperative overall survival and liver metastasis-free survival." (PMID 30282914, 2018).
metastatic cancers (2 papers, 2019 to 2023). A carcinoma which has spread from the original site of growth to another anatomic site. "EDA/EDB/‐containing cFn isoforms and TnC are also associated with solid tumors and metastatic cancers, wherein resident cancer cells activate the surrounding stromal fibroblasts, known as cancer‐associated fibroblasts (CAFs)." (PMID 31145503, 2019). "This prompted us to investigate the potential of TNC as a promising example of a target in multiple metastatic cancers." (PMID 37098922, 2023).
metastatic prostate carcinoma (2 papers, 2021 to 2024). A carcinoma that arises from the prostate gland and has spread to other anatomic sites. "In this context, PRO-C12 could be used as a tool to monitor the efficacy of anticancer treatments that disrupt the α9 integrin-tenascin-C interaction and improve the prognosis of patients with metastatic prostate cancer." (PMID 39048763, 2024).
nasopharyngeal carcinoma (2 papers, 2024 to 2025). A carcinoma arising from the nasopharyngeal epithelium. "Additionally, TNC promotes epithelial–mesenchymal transition in nasopharyngeal carcinoma and activates the PI3K/AKT/mTOR signaling pathway, collectively supporting its role as an oncogene." (PMID 41227351, 2025). "In nasopharyngeal cancer, Circlpo7 interacts with cytoplasmic YB1, promoting the phosphorylation of YB1 at S102, further promoting YB1’s nuclear translocation, and activating FGFR1, TNC, and NTRK1 transcription, thereby promoting nasopharyngeal cancer metastasis and resistance to cisplatin." (PMID 39497723, 2024).
neuroblastoma (2 papers, 2014 to 2015). Neuroblastoma (NB) is the most common solid, extracranial childhood tumor. "We have previously demonstrated that Tenascin-C (TNC)+ human neuroblastoma (NB) cells transdifferentiate into tumor-derived endothelial cells (TDEC), which have been detected both in primary tumors and in tumors formed by human NB cell lines in immunodeficient mice." (PMID 25362644, 2014).
ocular hypertension (2 papers, 2013 to 2017). Abnormally high intraocular pressure. "Tenascin C was also found to be upregulated in optic nerves of patients with open-angle glaucoma and in a rat ocular hypertension model, suggesting that tenascin C expression in the optic nerve may be an useful marker of glaucomatous damage." (PMID 23826199, 2013).
ovarian tumor (2 papers, 2015 to 2023). "It was shown that expression of tenascin-C is increased in ovarian tumours compared with benign tumours and this may be associated with induction of specific isoforms." (PMID 26090390, 2015). "TNC, FN1 and COL1 expression in in ascites or ovarian tumor tissue are associated with an unfavorable prognosis and a lower survival (proteinatlas.org, accessed on 10/01/2023)." (PMID 38264656, 2023).
pancreatic ductal adenocarcinoma (2 papers, 2023 to 2026). An infiltrating adenocarcinoma that arises from the epithelial cells of the pancreas. "It was also reported that in pancreatic ductal adenocarcinoma (PDA) cells, cell-surface annexin A2 promotes cancer cell invasion and metastasis upon binding with the extracellular matrix component tenascin C (TNC)." (PMID 37091157, 2023).
peripheral nerve injury (2 papers, 2013 to 2019). Injury to a peripheral nerve. "It is also reported that the expression of Tenascin-C occurs within two days after removal of epiperineurium as part of the regenerative response and its upregulation is an important prerequisite for axonal regrowth after peripheral nerve injury." (PMID 23282009, 2013).
pneumonia (2 papers, 2021 to 2023). An acute, acute and chronic, or chronic inflammation focally or diffusely affecting the lung parenchyma, caused by an infection in one or both of the lungs (by bacteria, viruses, fungi, or mycoplasma.). "For this purpose, we performed in vivo experiments inducing pneumonia in TNC deficient (TNC−/−) and wild-type (TNC+/+) mice by infection with MRSA via the airways." (PMID 34319124, 2021). "In this study, we examine the pathobiology of MRSA-induced pneumonia in a model of TNC-sufficient and TNC-deficient mice." (PMID 34319124, 2021). "With regard to cytokine release and systemic inflammation IL-1RA, tenascin-C, and sCD163 increased from baseline to the day of pneumonia diagnosis, IL-6, IL-10, procalcitonin and sRAGE decreased, and IL-8, MMP-8, and sTREM-1 remained unchanged in cases." (PMID 37415223, 2023). "TNC mRNA was induced in the lung transiently during MRSA-induced pneumonia, with a strong induction at 6 h after infection, decreasing thereafter." (PMID 34319124, 2021).
prostate intraepithelial neoplasia (2 papers, 2017 to 2021). A neoplastic proliferation of the epithelial cells that line the acini and the ducts of the prostate gland. "PCSCs from mPIN (mouse prostate intraepithelial neoplasia, a precursor lesion to murine PCa) used TNC (Tenascin-C), an ECM disulfide-linked hexameric glycoprotein, as a strategy to overcome immune surveillance." (PMID 29152153, 2017).
prostate tumor (2 papers, 2015 to 2021). "Findings were similar for TNC with a significant increase in the cribriform prostate tumor microenvironment of the lesser abundant ASPN+TNC− cells and ASPN+TNC+ cells in benign prostate stroma and a corresponding significant decrease in the more abundant ASPN−TNC+ cells in benign prostate stroma." (PMID 33600062, 2021).
sarcoidosis (2 papers, 2011 to 2025). Sarcoidosis is a multisystemic disorder of unknown cause characterized by the formation of immune granulomas in involved organs. "Reanalysis of a sarcoidosis scRNA-seq dataset revealed that, similar to NL and NXG, sarcoidosis lesional fibroblasts expressed high levels of MHC (e.g., HLA-B and HLA-DRA), CD74, PLOD2, STAT1, TNC, PRSS23, PSMB9, and CXCL9." (PMID 39989459, 2025).
sarcoma (2 papers, 2007 to 2021). A usually aggressive malignant neoplasm of the soft tissue or bone. "We have shown that established Rh30 and RD sarcoma cell lines cultured in the presence of the tested PRMT inhibitors have decreased expression of TNC, NRP1, MYOF, EMP1, OLFML3 and CCND1 and increased expression of the GADD45G gene." (PMID 34360791, 2021).
synovitis (2 papers, 2016 to 2019). Inflammation of a synovial membrane. "Tenascin-C is expressed early in the development of RA, even before disease diagnosis, with higher levels in the joints of people with synovitis who eventually developed RA than in people whose synovitis spontaneously resolved." (PMID 30552174, 2019).
T-cell non-Hodgkin lymphoma (2 papers, 2018). A non-Hodgkin lymphoma of T-cell lineage. "total of 100 diagnostic biopsies from patients with T-cell NHL were evaluated for immunohistochemical (IHC) tenascin-C expression with Tenatumomab." (PMID 29515769, 2018). "In the present study, we evaluate the presence of tenascin-C using Tenatumomab antibody in a series of diagnostic biopsies of T-cell NHL patients." (PMID 29515769, 2018). "In the present study, we evaluated for the first time the IHC expression of tenascin-C in T-cell NHL using Tenatumomab, a monoclonal antibody in clinical development for RIT application." (PMID 29515769, 2018). "The constant overexpression of the tenascin-C gene was observed in two independent publicly available T-cell NHL gene expression datasets." (PMID 29515769, 2018). "To further assess the expression of tenascin-C by T-cell NHL, we evaluated the presence at mRNA level of TNC using publicly available reports." (PMID 29515769, 2018). "Most of the systemic T-cell NHL (59%) were characterized by a diffuse expression (> 50%) of tenascin-C, while this was the case only in a minority of patients with MF/SS (21%) and pcALCL (50%)." (PMID 29515769, 2018). "In conclusions, tenascin-C represents an attractive target that sets the rationale to investigate the therapeutic activity of radiolabeled Tenatumomab in T-cell NHL." (PMID 29515769, 2018). "Most of the systemic T-cell NHL showed both strong and diffuse tenascin-C expression, especially ALCL and AITL histology." (PMID 29515769, 2018). "In conclusion, our data show that Tenatumomab is able to reveal the expression of tenascin-C in systemic T-cell NHL." (PMID 29515769, 2018). "Aim of the study was to evaluate tenascin-C expression within pathologic tissue of T-cell NHL and determine its clinical significance." (PMID 29515769, 2018). "Expression values of Tenascin-C microarray probes were extracted for normal and T-cell NHL samples." (PMID 29515769, 2018). "Multivariate models adjusted for age, gender and IPI were calculated to analyze the impact of the histologic characteristic of tenascin-C expression with PFS and OS in the 75 systemic T-cell NHL patients." (PMID 29515769, 2018). "We used an immunohistochemistry approach using the anti-tenascin-C monoclonal antibody Tenatumomab in 75 systemic T-cell NHL (including 72 mature and 3 precursor T-cell NHL), and 25 primary cutaneous T-cell NHL." (PMID 29515769, 2018).
temporal lobe epilepsy (2 papers, 2018 to 2021). A localization-related (focal) form of epilepsy characterized by recurrent seizures that arise from foci within the temporal lobe, most commonly from its mesial aspect. "Brains of temporal lobe epilepsy patients who exhibit Ammon's horn sclerosis show that tenascin-C is increased in the hippocampus and that tenascin-C undergoes a redistribution in which expression patterns become disrupted." (PMID 29531525, 2018).
tuberculosis (2 papers, 2011 to 2017). A chronic, recurrent infection caused by the bacterium Mycobacterium tuberculosis. "Concentrations of matricellular proteins tenascin C and TIMP-1 were increased in patients with HIV-tuberculosis, and higher concentrations were associated with decreased survival time." (PMID 28363198, 2017). "Concentrations of tenascin C and TIMP-1, both markers of matricellular metabolism, were higher in patients with HIV-tuberculosis." (PMID 28363198, 2017). "This is in agreement with findings of previous studies that have demonstrated increased levels of tenascin C and TIMP-1 in patients with active tuberculosis, with even higher concentrations measured at the site of infection." (PMID 28363198, 2017).
Acanthamoeba infection (1 paper, 2019). "In our study, 3 patients with CNV following Acanthamoeba infection were analyzed and we surprisingly found that they showed the highest concentration of FN1 and TNC (+116%, p = 0.044 + 49.5% p = 0.012 compared to non-Acanthamoeba CNV patients)." (PMID 31582785, 2019).
Acanthamoeba keratitis (1 paper, 2019). Keratitis due to infection by acanthamoeba; it is usually associated with soft contact lens wear, particularly overnight wear. "Interestingly, among CNV patients, those affected with Acanthamoeba keratitis showed the highest levels of fibronectin-1 and tenascin-C, suggesting a specific role of these two proteins in Acanthamoeba driven corneal CNV." (PMID 31582785, 2019).
acne (1 paper, 2019). An inflammatory process of the sebaceous glands which is characterized by comedones, nodules, papules and/or pustules on the skin. "However, the roles of TNC and SPP1 in acne have not been reported until now." (PMID 31281837, 2019).
adhesive capsulitis (1 paper, 2016). "The synovium/capsule samples from the patients with adhesive capsulitis had significantly higher TNC and FN1 expression than those from the controls." (PMID 27438566, 2016). "The patients with adhesive capsulitis had higher levels of TNC (p=0.005) and FN1 (p=0.043) expression compared to the controls." (PMID 27438566, 2016). "In this study, we found higher levels of TNC and FN1 expression in glenohumeral synovium/capsule samples collected from patients with adhesive capsulitis compared to those collected from controls." (PMID 27438566, 2016). "In the present study, we quantified the mRNA expression of the TGFβ1, TGFβR1, LOX, PLOD1, PLOD2, COMP, FN1, TNC and TNXB genes in glenohumeral synovium/capsule samples collected from patients with adhesive capsulitis and from controls." (PMID 27438566, 2016). "As such, TNC, FN1 and TGFβ1 receptor I may also play roles in adhesive capsulitis by contributing to capsule inflammation and fibrosis." (PMID 27438566, 2016).
aneurysm (1 paper, 2021). Bulging or ballooning in an area of an artery secondary to arterial wall weakening. "Some authors believe that Tenascin-C could be a candidate biomarker, but these studies are still inconclusive with regard to its role in the clinical outcomes of patients with aneurysms." (PMID 34456984, 2021).
Arrhythmia (1 paper, 2016). Any cardiac rhythm other than the normal sinus rhythm. "TnC L48Q mice also had lower left ventricular dilation and showed no arrhythmia or differences in heart rate variability in conscious and unrestrained TnC L48Q mice." (PMID 26908229, 2016).
autism (1 paper, 2015). Persistent deficits in social interaction and communication and interaction as well as a markedly restricted repertoire of activity and interest as well as repetitive patterns of behavior. "The patient showed all the typical features of Autism, WES revealed a de novo frameshift mutation in CREBBP and de novo sequence variants in TNC and IGFALS genes." (PMID 25768348, 2015).
autoimmune myocarditis (1 paper, 2024). Autoimmune myocarditis is an autoimmune disease that affects the heart. "Tenascin-C, a nonstructural extracellular matrix glycoprotein expressed during heart injury and remodeling, aggravates autoimmune myocarditis via dendritic cell activation and Th17 cell differentiation." (PMID 39026189, 2024).
B-cell NHL (1 paper, 2018). "The clinical feasibility of targeting tenascin-C expressed in the microenvironment of B-cell NHL and Hodgkin lymphoma has been previously reported." (PMID 29515769, 2018). "Differently from Hodgkin and B-cell NHL, we observed that tenascin-C was expressed in the cytoplasm of PTCL, in particularly in a proportion of ALCL (32%) and AITL (44%) cases, and it was associated to a diffuse stromal and perivascular tissue expression." (PMID 29515769, 2018). "Our findings are in line with previous reports in pathological samples of B-cell NHL and Hodgkin disease with different anti tenascin-C antibodies." (PMID 29515769, 2018).
Behçet's disease (1 paper, 2024). "A previous study on Behçet's disease did not report an increase in tenascin-C levels." (PMID 39114190, 2024).
benign prostatic hyperplasia (1 paper, 2020). A non-cancerous nodular enlargement of the prostate gland. "Given that TNC expression was found elevated from 0% in benign prostatic hyperplasia (BPH) stroma to 47% in tumor-associated stroma, its detection in circulation and its immunomodulatory role indicate TNC as a promising drug target and disease-determining factor." (PMID 33334054, 2020).
biliary tract cancer (1 paper, 2020). "In all, 30 tumors from patients with biliary tract cancers ranging in age from 29–79 years old were processed for histopathological examination as well as anti-tenascin-C and anti-tenascin-W immunohistochemistry." (PMID 33692777, 2020). "Here we used immunohistochemistry to study the expression of tenascin-C and tenascin-W in the stroma of ICC, CPHBD and CGB, and we characterized biliary tract cancer-derived cell lines for tenascin-W expression." (PMID 33692777, 2020).
Bowen’s disease (1 paper, 2022). "And next, among 20 proteins, 8 proteins (TNC, FSCN1, SERPINB1, ACTN1, RAB31, COL3A1, COL1A1 and CD36) expressed levels showed significant differences between CSCC and Bowen disease." (PMID 36085041, 2022). "Furthermore, the relative expression levels of TNC, FSCN1, SERPINB1 in the Bowen disease were also significantly increased, while the COL3A1 were also significantly decreased relative to the healthy control." (PMID 36085041, 2022). "Besides, the proteins of TNC, FSCN1, SERPINB1, ACTN1 and RAB31 in CSCC were significantly up-regulated, while COL3A1, COL1A1 and CD36 were significantly down-regulated relative to Bowen disease in proteomics results." (PMID 36085041, 2022).
bruxism (1 paper, 2025). Excessive clenching of the jaw and grinding of the teeth. "The most important result of the study is the independent association between phasic bruxism and the TnC concentration, as well as between tonic bruxism and TSP-1." (PMID 41010873, 2025). "The regression analysis revealed that TnC levels are significantly associated with phasic bruxism episodes (p = 0.035), smoking (p = 0.045), and age (p = 0.031)." (PMID 41010873, 2025). "Since severe bruxism occurs >4 times per hour, the study results indicate a possible relationship between TnC and TSP-1 and SB in cases of very severe bruxism." (PMID 41010873, 2025).
Cerebral ischemia (1 paper, 2025). Restriction of arterial blood supply to the brain associated with insufficient oxygenation to support the metabolic requirements of the tissue. "Future research may clarify the molecular mechanisms by which cerebral ischemia regulates the expression of TNC and GJA1." (PMID 40003865, 2025). "Our previous transcriptomic analysis revealed the significant upregulation of TNC and GJA1 in the SVZ following transient global cerebral ischemia." (PMID 40003865, 2025).
Cholecystitis (1 paper, 2020). The presence of inflammatory changes in the gallbladder. "Similarly, tenascin-C immunoreactivity is seen surrounding blood vessels in the adventitia of a non-tumoral gallbladder removed from a patient with cholecystitis, around bundles of smooth muscle in the muscularis externa, and in the lamina propria of the mucosa." (PMID 33692777, 2020). "However, in contrast to anti-tenascin-C, anti-tenascin-W did not immunostain normal liver, non-tumoral liver from 3 patients with ICC, or tissues from 5 of the 6 gallbladders removed from patients with cholecystitis." (PMID 33692777, 2020).